RNU6-1021P (RNA, U6 small nuclear 1021, pseudogene)
Gene: Small nuclear RNA gene on chromosome 18 (14,531,676 to 14,531,782, reverse strand). Ensembl gene ENSG00000200132.
Homologues: Orthologues: chimpanzee U6 (100% identical), macaque U6 (93% identical), macaque U6 (91% identical), guinea pig U6 (79% identical), dog U6 (77% identical), pig U6 (69% identical). Paralogues in human: RNU6-286P (99% identical), RNU6-631P (99% identical), RNU6-749P (99% identical), U6 (99% identical), RNU6-127P (94% identical), RNU6-1239P (93% identical), RNU6-1268P (93% identical), RNU6-473P (93% identical), RNU6-617P (93% identical), RNU6-816P (93% identical), RNU6-848P (93% identical), RNU6-1049P (93% identical), and 1286 more.